INS (insulin)
Diseases named in the same sentence as INS in open-access papers (continued):
Sharing a sentence is not in itself a finding about the gene and the disease.
type 2 diabetes (continued). "The molecular picture from these studies is consistent with our understanding of type 2 diabetes pathophysiology; under normal conditions, transient increases in blood glucose stimulate insulin secretion." (PMID 37333221, 2023). "In conclusion, this study suggests that fully closed-loop insulin delivery is a safe and efficacious approach to manage type 2 diabetes in adults." (PMID 36631592, 2023). "In this manner, leptin resistance should lead to peripheral (adipose tissue, liver, and muscle) insulin resistance and islet beta-cell apoptosis, paving the way to Type 2 diabetes." (PMID 38260129, 2023). "Adipose tissues secrete a lot of adipokines, such as leptin, resistin, and adiponectin which is closely related to type 2 diabetes because of its effect on insulin sensitivity and inflammation." (PMID 37371606, 2023). "Present consensus, still to be adequately validated, is that although the lean individuals with type 2 diabetes had a similar pathophysiology concerning their insulin resistance as the obese individual, their insulin secretory defects are much more severe." (PMID 37762318, 2023). "In type 2 diabetes, therapeutic failure to the oral anti diabetics is frequent, the use of schemes with basal insulin or with multiple doses of insulin (basal insulin and short-acting insulins) are a widely accepted way to intensify therapy." (PMID 37185053, 2023). "In type 2 diabetes, the tissues are insulin resistant and therefore cannot absorb glucose and/or insufficient insulin production by the pancreas." (PMID 38084156, 2023). "A meta-analysis showed that oral magnesium supplementation and appropriate dietary patterns improve insulin sensitivity and metabolic control in individuals with type 2 diabetes." (PMID 36837924, 2023). "All of these factors are connected to impaired insulin sensitivity, which is a prominent characteristic of type 2 diabetes." (PMID 37568405, 2023). "A 55-year-old female with a medical history of asthma on inhaled steroids and type 2 diabetes on insulin therapy was diagnosed with systemic sarcoidosis three weeks before admission." (PMID 38031167, 2023). "In this sensitivity analysis, we detected an increased adjusted HR for type 2 diabetes requiring insulin treatment in the cancer group (except pancreatic cancer), compared with the non-cancer group (adjusted HR, 1.35; 95% CI, 1.07–1.69)." (PMID 36831436, 2023). "IP6-generated IPPs also have a role in insulin secretion and sensitivity; IP6-kinase 1 has been shown to regulate insulin secretion and signaling, which can be targeted in type 2 diabetes therapy." (PMID 37371493, 2023). "Out of the participants, 4,013 (44.7%) had type 2 diabetes, and 2,734 (30.5%) individuals underwent insulin therapy." (PMID 37833697, 2023). "Type 2 diabetes (T2D) is a leading contributor to global morbidity and mortality and is characterized by reduced insulin response in insulin-sensitive tissues and pancreatic islet beta cell dysfunction." (PMID 36757889, 2023). "Alarmingly, this age group is also at risk of imminent rises in childhood obesity-related comorbidities, including hypertension, insulin insensitivity, fatty liver, type-2 diabetes (T2D) and cardiovascular disease (CVD)." (PMID 37299488, 2023). "Insulin resistance (IR) is considered the reduced responsiveness of peripheral tissues to insulin, and it was observed that IR consequences take place several years before type 2 diabetes mellitus (T2DM)." (PMID 37374105, 2023). "Tirzepatide showed a significant reduction in LFC and VAT and in ASAT volumes compared with insulin degludec in this subpopulation of patients with type 2 diabetes in the SURPASS-3 study." (PMID 36909312, 2023). "Once hyperinsulinemia is confirmed by detecting FINS in a patient with insulin or insulin analog-treated type 2 diabetes, the FINS/CP ratio should be calculated and, subsequently, a more precise assay such as RIA, or PEG precipitation, carried out." (PMID 37324170, 2023).
type 2 diabetes (continued). "Insulin has a high propensity to aggregate and it forms amyloid deposits in patients with type II diabetes both with continuous subcutaneous insulin infusion and with repeated insulin injection." (PMID 36674821, 2023). "The DUAL VII trial confirmed that IDegLira has comparable glycaemic effects to MDI in patients with type 2 diabetes uncontrolled on basal insulin, but with less hypoglycaemia and a more beneficial effect on body weight." (PMID 36461758, 2023). "Type 2 diabetes develops when β-cells fail to secrete a compensatory amount of insulin to overcome the insulin resistance." (PMID 36837914, 2023). "In the case of type-2 diabetes, β-cell mass is reduced due to apoptosis and β cells secrete insulin asynchronously." (PMID 37446104, 2023). "Type 2 diabetes (T2D) is characterized by chronic hyperglycemia due to insufficient insulin secretion from pancreatic islets, often in combination with insulin resistance in target cells." (PMID 36656641, 2023). "Further, caffeine was able to reduce small intestinal glucose absorption, increase muscle glucose uptake ex vivo, improve pancreatic β-cell function and stimulate insulin secretions in an animal model of type 2 diabetes." (PMID 37143025, 2023). "Nutrigenetic research has investigated the interactions between SNPs influencing body composition, insulin signaling, and dietary factors in relation to adiposity and glucose homeostasis in obesity and type 2 diabetes." (PMID 37610590, 2023). "One study found that the upregulation of miR-375 in pancreatic beta-cells led to impaired insulin secretion and decreased beta-cell mass, indicating a potential role in the pathogenesis of type 2 diabetes." (PMID 38139275, 2023). "Although type 2 diabetes generally only occurs when pancreatic beta cells are incapable of secreting enough insulin to maintain normoglycemia, this most often occurs in the setting of insulin resistance." (PMID 37485059, 2023). "Type 2 diabetes mellitus (T2D) entails an alteration in the insulin and glucose metabolism (i.e., hyperglycemia)." (PMID 36833129, 2023). "The present study shows that fully closed-loop insulin delivery is a safe and effective approach to improve glycemic control in people with type 2 diabetes during 8 weeks of use in the outpatient setting." (PMID 36631592, 2023). "PI3K has a large impact on GLUT4, the insulin-regulated facilitative glucose transporter located downstream in the type 2 diabetes pathway." (PMID 36269347, 2023). "The efficacy and safety of the 52-week imeglimin treatment combined with insulin in Japanese patients with type 2 diabetes was evaluated by several authors." (PMID 37237539, 2023). "Tesaglitazar, a dual PPAR agonist with an affinity for PPARɑ/γ, can increase insulin sensitivity and is used in the treatment of type 2 diabetes." (PMID 37077915, 2023). "Lipotoxicity is a promising therapeutic target for various metabolic diseases, such as type 2 diabetes, ischemic heart disease, and insulin resistance of skeletal muscle." (PMID 36986221, 2023). "Consistently, a protein preload significantly decreases postprandial glycemia and increases plasma insulin levels in patients with type 2 diabetes, which is partially attributed to the elevation of GLP-1 and GIP levels." (PMID 37960324, 2023). "Simplification of insulin regimens is suitable for a lot of people with type 2 diabetes, but it is rarely carried out." (PMID 36461758, 2023). "We performed this additional analysis because insulin is an important regulator of autonomic function and levels of insulin are substantially higher in individuals with prediabetes than in individuals with type 2 diabetes and normal glucose metabolism." (PMID 37143089, 2023). "Previous studies have found that wnt5a promotes β-cell insulin secretion and reduced concentrations in patients with type 2 diabetes." (PMID 37255814, 2023).
type 2 diabetes (continued). "Although the preferred glucose-lowering medication in pregnancy is insulin, the most common initial glucose-lowering drug for type 2 diabetes is metformin, and many women experience unplanned pregnancy while on metformin therapy." (PMID 37401946, 2023). "GDM has also been linked to genes associated with maturity-onset diabetes (MODY), such as glucokinase (GCK, MODY2 gene) which is implicated in glucose signaling, glycogenesis and insulin secretion." (PMID 38288471, 2023). "Studying the effect of vitamin K4 on glycaemic control of individuals with type 2 diabetes in the current study revealed a significant decrease in the fasting serum insulin and HOMA-IR in the intervention group compared to the placebo group after 24 weeks." (PMID 37552330, 2023). "By enhancing insulin sensitivity, melatonin offers a comprehensive approach to managing the metabolic aspects of PCOS and potentially reducing the risk of type 2 diabetes." (PMID 38106751, 2023). "Multiple diabetic drugs can induce hypoglycemia, predominantly including, but not limited to, insulin in type 1 diabetes (T1D) and type 2 diabetes (T2D), and sulfonylureas (in T2D); there have also been associations with biguanides and thiazolidinediones." (PMID 37372995, 2023). "We carried out a trial to examine the safety and efficacy of switching from MDI to IDegLira in relatively well controlled (HbA1c ≤ 7.5% [58 mmol/mol]) but potentially overtreated subjects with type 2 diabetes using low total daily insulin dose (TDD)." (PMID 36461758, 2023). "Improved insulin sensitivity is pivotal in regulating glucose metabolism and preventing the onset of type 2 diabetes." (PMID 38106751, 2023). "The GLP-1R is a highly effective target for managing type 2 diabetes by increasing insulin secretion, which lowers blood glucose levels." (PMID 37085847, 2023). "A glucolipotoxic environment, similar to that observed in type 2 diabetes, is known to inhibit insulin biogenesis, vesicle budding, protein trafficking and ER lipid raft formation." (PMID 37537395, 2023). "Cinnamon was more likely to positively impact blood sugar and insulin in healthy individuals than those with type 2 diabetes." (PMID 38068725, 2023). "The activation and the nuclear accumulation of Fyn are partially stimulated by glycogen synthase kinase‐3β (GSK‐3β), which reduces insulin sensitivity and hepatic glycogen storage in type 2 diabetes." (PMID 37823118, 2023). "It turns out that this value is close to that observed in type 2 diabetes patients, in whom there is frequently a reduction in the requirement for insulin, reducing it by half, on average." (PMID 36771207, 2023). "Skeletal muscle ACS activity was upregulated by 74% following aerobic exercise training in the obese males/females with type 2 diabetes compared with before, concomitantly with improved whole‐body insulin sensitivity, documented by the lowering of HOMA‐IR." (PMID 37726199, 2023). "Tirzepatide is currently being studied in an ongoing trial as an alternative to prandial insulin in patients currently on a basal insulin to treat type 2 diabetes." (PMID 37526853, 2023). "Using MR Analysis, we found independent effects of type 2 diabetes, fasting insulin, and HbA1c on total testosterone and sex hormone-binding globulin after maximum exclusion of the effects of obesity, BMI, TG, LDL and Adiponectin." (PMID 37900148, 2023). "Compared to traditional insulin pens, subcutaneous injection of premixed insulin using a needle-free syringe is effective in controlling fasting blood glucose in patients with early onset type 2 diabetes and is less painful at the injection site." (PMID 36864833, 2023). "Type 2 diabetes (T2D) is a progressive disease characterized by insulin resistance, impaired insulin secretion (ß-cell dysfunction), and subsequent hyperglycemia." (PMID 36835790, 2023).
type 2 diabetes (continued). "A controlled trial found that FGF21 promotes glucose transport in the extensor digitorum longus muscle and soleus muscle of patients with type 2 diabetes to compensate for decreased insulin sensitivity." (PMID 38069273, 2023). "Type 2 Diabetes has historically been defined as a disease characterized by muscle, adipose and liver insulin insensitivity with lost functional β-cell mass, including dysregulated GSIS being a later occurrence resulting from long-term insulin insensitivity." (PMID 37512508, 2023). "We previously reported that hepatic insulin clearance is increased in patients with high HbA1c type 2 diabetes." (PMID 38115089, 2023). "Severe hypoglycemia in people with type 2 diabetes occurs in about 3–25% of individuals; however, this number is much higher in people with insulin-treated type 2 diabetes." (PMID 37887414, 2023). "A variety of therapeutic drugs have been used to treat type 2 diabetes, which mainly act by improving insulin resistance or directly supplementing insulin." (PMID 36982617, 2023). "Metformin, an oral anti-glycemic agent used to manage Type 2 Diabetes, Gestational Diabetes and Polycystic Ovary Syndrome, acts by inhibiting gluconeogenesis and enhancing insulin sensitivity in peripheral tissues." (PMID 37510816, 2023). "C-peptide has been shown to be a useful test to assess the degree of residual endogenous insulin secretion in patients with type 1 and type 2 diabetes." (PMID 37589043, 2023). "In line with this, we found that insulin levels during an OGTT are substantially higher in prediabetes than in type 2 diabetes and normal glucose metabolism (also in the present dataset [data not shown])." (PMID 37143089, 2023). "In early type 2 diabetes, the strategy of “induction” with short-term intensive insulin therapy followed by “maintenance” with metformin can stabilize pancreatic beta-cell function in some patients but not others." (PMID 37500612, 2023). "This study aimed to investigate the clinical implications of fasting serum insulin (FINS) levels in subjects with type 2 diabetes who were receiving insulin therapy." (PMID 37324170, 2023). "Comparison of insulin degludec/insulin aspart and biphasic insulin aspart 30 in uncontrolled insulin-treated type 2 diabetes: a phase 3 a, randomized, treat-to-target trial BOOST: Intensity Premix I Investigators." (PMID 37101024, 2023). "The DEVOTE cardiovascular outcomes trial comparing insulin degludec (degludec) versus insulin glargine 100 U/mL (glargine U100) in a type 2 diabetes (T2D) population included many participants with 8-point glucose profiles and adjudicated events." (PMID 37017470, 2023). "Type 2 diabetes is a disease in which endogenous insulin is secreted to some extent, but hyperglycemia occurs due to impaired insulin secretion or insulin resistance." (PMID 37239172, 2023). "Phase 2 clinical trials up to 26 weeks in insulin-naive or previously insulin-treated individuals with type 2 diabetes have shown low rates of level 2 and level 3 hypoglycaemia for once-weekly icodec that are comparable to once-daily glargine U100." (PMID 37308751, 2023). "Hypoglycemia is less common in patients with insulin-treated type 2 diabetes (T2D), with 3–25% of patients experiencing at least one severe episode annually." (PMID 37298308, 2023). "In-depth research on it will explore more effective insulin treatment methods and provide a better therapeutic approach in the treatment of early-onset type 2 diabetes." (PMID 36864833, 2023). "The objective of this study was to determine the idealistic, realistic, and unrealistic expectations of pharmacological medication (metformin, insulin, and glyburide) among persons with type 2 diabetes in primary care." (PMID 36817935, 2023). "That same IL-1B is a target for many drugs tied to type 2 diabetes to "improve insulin secretion and action and glycemic control"." (PMID 37255905, 2023).
type 2 diabetes (continued). "Alterations in β cells induce changes in mitochondrial dynamics, impair the secretion of insulin mediated by glucose, and lead to the onset of type 2 diabetes." (PMID 37109219, 2023). "Imeglimin increases insulin secretion in a glucose-dependent manner, and also exerts beneficial effects on β-cell mitochondrial integrity in type 2 diabetic mice." (PMID 37237539, 2023). "Disordered eating behaviours have been reported to be quite common in young adults with type 2 diabetes receiving insulin therapy." (PMID 36809582, 2023). "The treatments for type II diabetes mainly include diet control, exercise regimens, oral medication, insulin therapy, and the recent trend of surgery." (PMID 36771306, 2023). "It is characterized by glycemic dysregulation due to the body’s inability to secrete insulin (type 1 diabetes) or insulin resistance (type 2 diabetes)." (PMID 38139380, 2023). "Despite the detection of several AQPs in the endocrine pancreas, only AQP7 has been shown to date to participate in insulin secretion, and to undergo deregulation in type 2 diabetes that can be rescued by hypoglycemic drugs." (PMID 37681902, 2023). "Current treatments for type 2 diabetes include diet, exercise and oral antidiabetic drugs; for some patients, insulin therapy is required over time." (PMID 36773074, 2023). "Inhibition of HSL activity can prevent the accumulation of free fatty acids, improve insulin sensitivity and control of blood glucose in type 2 diabetes." (PMID 37830580, 2023). "Current treatment strategies for type 2 diabetes generally involve pharmacological treatment aimed at stimulating insulin secretion or increasing sensitivity to insulin." (PMID 37050137, 2023). "As PTPN2 and PTPN6 have been shown to negatively regulate insulin action, the identification of inhibitors of these proteins is considered an effective strategy for the treatment or prevention of type 2 diabetes." (PMID 37374154, 2023). "Type 2 diabetes (T2D) is mediated by the inability of muscle, liver, and fat cells to adequately respond to insulin signaling, which normally results in blocking the release of glucose." (PMID 37215983, 2023). "In vitro studies on murine beta cell lines and human pancreatic islets have identified endoplasmic reticulum (ER) stress as a mechanism leading to beta cell failure, increased proinsulin misfolding and decreased insulin production in type 2 diabetes." (PMID 36280617, 2023). "As a result of the body's cells losing sensitivity to insulin, type 2 diabetes is thought to be characterized by an increase in blood sugar levels." (PMID 38050514, 2023). "Nevertheless, impairment of insulin signaling can trigger metabolic imbalances that result in obesity and related diseases like type 2 Diabetes Mellitus (T2DM)." (PMID 37762063, 2023). "The main pathology of uncontrolled type 2 diabetes is resistance to insulin in body tissues and/or defective insulin excretion from the pancreas." (PMID 37398707, 2023). "TZD class PPARG agonists have been widely used clinically as insulin sensitizers to treat type 2 diabetes." (PMID 37569334, 2023). "IL-1 together with TNFα inhibits insulin synthesis, suppresses insulin-induced secretion, and induces apoptosis in pancreatic β-cells, leading to type 1 and type 2 diabetes." (PMID 36647426, 2023). "Studies have shown that zinc glycoprotein levels are decreased in obesity and type 2 diabetes, and supplementation with zinc can improve insulin sensitivity and glucose metabolism." (PMID 37047011, 2023). "In hospitalized subjects with severe COVID-19 infection, insulin is the preferred treatment for type 2 diabetes with the use of continuous glucose monitoring." (PMID 38292772, 2023). "Numerous studies have demonstrated the clinical benefits of continuous glucose monitoring (CGM) in individuals with type 1 diabetes (T1D) and type 2 diabetes (T2D) who are treated with intensive insulin regimens." (PMID 37471068, 2023).